SLC5A5 (solute carrier family 5 member 5)
Diseases named in the same sentence as SLC5A5 in open-access papers (continued):
Sharing a sentence is not in itself a finding about the gene and the disease.
thyroid dyshormonogenesis (7 papers, 2018 to 2024). "In the enrichment analysis, 13 signal transduction pathways, including FGFR4 mutant receptor activation and Defective SLC5A5 causing thyroid dyshormonogenesis 1, were involved in the effect of selenium on eGFR levels." (PMID 39329105, 2024). "Eleven pathways, including thyroxine biosynthesis and defective SLC5A5 causes thyroid dyshormonogenesis were found to mediate the effects of selenium levels on renal function in the enrichment analysis." (PMID 39329105, 2024). "The reported mutations of SLC5A5 almost all affect its normal functional activity, leading to thyroid dyshormonogenesis." (PMID 33815280, 2021). "The mutation of SLC5A5 is a cause of thyroid dyshormonogenesis, which leads to CH in patients." (PMID 33815280, 2021). "Mutations in genes critical for TH biosynthesis, including sodium iodide symporter (NIS; SLC5A5), pendrin (PDS; SLC26A4), thyroglobulin (TG), thyroperoxidase (TPO), thyroid stimulating hormone receptor (TSHR), and dual oxidase 2 (DUOX2), have been causally linked to thyroid dyshormonogenesis." (PMID 38281222, 2024).
Graves disease (6 papers, 2018 to 2023). Graves' disease is an autoimmune disorder that leads to overactivity of the thyroid gland (hyperthyroidism).It is caused by an abnormal immune system response that causes the thyroid gland to produce too much thyroid hormones. "The genes related to the antithyroid effects of long-term iodine loading are Slc5a5, Slc26a4, Duox2, and Duoxa2, in addition to Tpo, Dio1, and Slco4a1, which are upregulated in Graves' hyperthyroidism." (PMID 36565031, 2023).
liver cancer (6 papers, 2014 to 2025). An epithelial or non-epithelial malignant neoplasm that arises from the liver.
thyroid nodule (5 papers, 2017 to 2020). A small circumscribed mass in the THYROID GLAND that can be of neoplastic growth or non-neoplastic abnormality. "The expression of SLC5A5 was highly sensitive and specific, suggesting that it might be an effective biomarker for preoperative blood-based diagnosis of thyroid nodules." (PMID 30781659, 2019). "Limitations aside, this is the first report to show that the expression of SLC5A5 in blood may be effective for the preoperative evaluation of thyroid nodules." (PMID 30781659, 2019). "For validation, the expression of SLC5A5 and LGALS3 was measured in a larger number of thyroid nodule patients." (PMID 30781659, 2019).
follicular adenomas (4 papers, 2012 to 2024). "When patients with malignant nodules were divided into subgroups, we found that the expression of SLC5A5 in follicular-type thyroid carcinomas was different from that in benign nodules (follicular adenomas)." (PMID 30781659, 2019). "Moreover, a previous study suggested that SLC5A5 expression could differentiate between follicular adenomas and carcinomas." (PMID 38136890, 2023).
lymph node metastases (4 papers, 2018 to 2024). "Gene expression analysis revealed that SLC5A5 was down-regulated in males, younger individuals, and those with lymph node metastasis, and a lower level of SLC5A5 was associated with a worse disease-free survival(P<0.05)." (PMID 38974575, 2024). "In addition to our findings, we discovered that in male and younger patients, the expression of SLC5A5 is downregulated, mirroring its expression in tissue with lymph node metastasis." (PMID 38974575, 2024).
testicular cancer (3 papers, 2014 to 2025). A primary or metastatic malignant neoplasm that affects the testis. "Survival analysis revealed a significant association between SLC5A5 expression and recurrence risk in testicular cancer patients (p = 0.017, HR = 2.47, 95% CI: 1.175–5.193)." (PMID 40321316, 2025). "Additionally, the identification of SLC5A5 and other candidate markers provides a broader framework for understanding testicular cancer heterogeneity and developing targeted diagnostic strategies." (PMID 40321316, 2025). "Cancer of the testis is the most frequent cancer in young men, and nearly all germ cell testicular tumors, but not Leydig cell tumors, express SLC5A5, making radioiodine a possible therapy." (PMID 35899258, 2022).
testis tumors (2 papers, 2014 to 2025). "While SLC5A5 expression was generally low across various malignancies, it was markedly upregulated in testicular tumors, underscoring its potential as a tumor-specific marker." (PMID 40321316, 2025).
Breast Invasive Carcinoma (1 paper, 2025). "In the Breast Invasive Carcinoma (TCGA, Firehose Legacy) dataset, the TNBC subgroup comprised n = 69 samples, among which only 1 case exhibited a FOXA1 mutation (with no available mRNA expression data for NIS/SLC5A5), while the remaining samples were FOXA1 wild-type." (PMID 41283251, 2025).
epidermoid carcinoma (1 paper, 2025). "SLC5A5 transcripts were detected in the following SG cell lines: the human submandibular SG epidermoid carcinoma (A253) and the mouse submandibular SG adenocarcinoma (WR21), as shown by quantitative PCR (qPCR)." (PMID 40508009, 2025).
seminoma (1 paper, 2025). A radiosensitive malignant germ cell tumor found in the testis (especially undescended), and extragonadal sites (anterior mediastinum and pineal gland). "Seminoma patients with high SLC5A5 expression had a markedly increased risk of recurrence, with an approximately tenfold greater risk compared to those with low expression (p = 0.032, HR = 10.31, 95% CI: 1.275–83.344)." (PMID 40321316, 2025). "Among these, SLC5A5 and SPTBN4 emerged as risk factors for seminoma, whereas PLD4 was identified as a protective factor." (PMID 40321316, 2025). "Results: scRNA-seq analysis revealed heterogeneous epithelial populations, with Epi1 cells exhibiting SLC5A5 and SPTBN4 as risk factors for advanced progression of seminomas." (PMID 40321316, 2025).
tumor (235 papers, 2005 to 2026). "Moreover, SLC5A5 mRNA expression was significantly lower in mutated PTCs and a lower SLC5A5 mRNA expression was associated with tumor aggressiveness and worse prognosis." (PMID 29298843, 2018). "Key mechanisms include the induction of a tumor-suppressive gene network involving thyroid differentiation markers (e.g., NIS/SLC5A5, TG, PAX8) and repression of oncogenic drivers like RUNX2." (PMID 41153831, 2025). "Our study findings also revealed a noteworthy 2.5-fold upregulation of SLC5A8 and a 2.4-fold upregulation of SLC5A5 in the TERT-negative tumor as compared to the TERT-positive tumor." (PMID 38642578, 2024). "The expression level of IL37 in the tumor was significantly higher than that in the normal tissues, while SLC5A5, NR4A3, and ODF3L1 were highly expressed in normal tissues than those in tumors." (PMID 34248843, 2021). "Recently, it was demonstrated that the SLC5A5 mRNA expression is more reliable than immunohistochemical expression of sodium iodide symporter (NIS) coded by SLC5A5 gene regarding tumor behavior, therapeutic response, and prognostic outcomes." (PMID 32486143, 2020). "The significantly lower SLC5A5 expression in cases presenting vascular invasion and extrathyroidal extension suggests that a decreased SLC5A5 expression may be associated to an aggressive tumor behavior and thus may help to characterize patients at risk for poor therapy response." (PMID 29298843, 2018). "SLC5A5 mRNA expression is more informative than NIS immunohistochemical expression regarding tumor aggressiveness and prognostic features." (PMID 29298843, 2018). "In 43/49 (87%) tissue pairs, the expression of SLC5A5 was lower in tumor than in control tissue." (PMID 34199867, 2021). "Similarly, nonseminomatous tumor patients with high SLC5A5 expression exhibited a twofold increased recurrence risk (p = 0.061, HR = 2.31, 95% CI: 0.961–5.537)." (PMID 40321316, 2025). "Since larger tumors are associated with higher recurrence rates and worse prognosis, the significantly lower SLC5A5 expression in tumors larger than 2 cm may be considered as an additional fact linking lower SLC5A5 mRNA expression with higher tumor aggressiveness." (PMID 29298843, 2018). "Six genes—ARHGEF19, CORO1A, ACOT7, ZC3H18, SLC5A5, and ZFAS1—showed statistically significant differential expression between tumor and normal tissues (P < 0.05)." (PMID 40070828, 2025). "DEG analyses revealed the genes contributing to RFS and related to SUVmax (PSG5, TFF3, SOX2, SLC5A5, and SLC5A7) and tumor size (HOXD10, IFNA1, and FER1L6)." (PMID 38745021, 2024). "Specifically, both SLC5A5 and AVPR1A were downregulated in tumor and LNM tissues." (PMID 38974575, 2024). "This non-germline approach first relies upon the stable introduction of constitutive and tumor specific expression of murine NIS (mNIS; sodium iodide symporter; Slc5a5), which can confer sensitive in vivo tumor imaging via the uptake of radioactive isotopes of iodide or their radioanalogues." (PMID 37664695, 2023). "The tumor-specific sodium iodide symporter gene, NIS (also known as SLC5A5), is also expressed." (PMID 35267472, 2022). "Of note, patients with PTC that developed recurrences and/or distant metastases presented lower levels of SLC5A5 mRNA expression compared to patients without tumor progression." (PMID 29757257, 2018). "Moreover, we also addressed the impact of the genetic background of the tumor on SLC5A5 and NIS expression as well as its targeting to the basolateral cell membrane." (PMID 29298843, 2018). "On the contrary to previous reports, in our cohort SLC5A5 expression in tumor did not depend on BRAFV600E status, but this may result from population differences." (PMID 34199867, 2021).
tumor (continued). "In contrast, in the patient showing re-induction of RAI uptake following treatment with larotrectinib, her tumor was negative for TERT promoter mutations and showed high TDS with no downregulation of the apical iodide transporter (SLC5A8) and the sodium–iodide symporter (SLC5A5) gene expression." (PMID 38642578, 2024). "Finally, no significant changes were observed on the expression of genes related to thyroid cell differentiation (TG, TPO, SLC5A5 and TSHR) key players on the tumor progression and survival rates in PTC (data not shown)." (PMID 36776296, 2023).
cancer (123 papers, 2007 to 2026). A tumor composed of atypical neoplastic, often pleomorphic cells that invade other tissues. "SLC5A8 is a sodium-coupled mono carboxylate transporter; methylation of the SLC5A8 gene is essential in human cancers, and the protein encoded by this gene shows structural features of a sodium-iodide symporter with 48% homology to SLC5A5 (610 amino acids)." (PMID 28926589, 2017). "In cancers in general, survival is significantly improved when SLC5A5 is highly expressed compared with when its expression is low (p = 0.0019)." (PMID 36769088, 2023). "The incorporation of radioiodine by cancer cells is mediated by sodium iodide symporter (NIS) (codified by the SLC5A5 gene), that is functional only when targeted to the cell membrane." (PMID 29298843, 2018). "In our series, SLC5A5 expression was lower in carcinomas with vascular invasion and with extrathyroidal extension and in those harboring BRAFV600E mutation." (PMID 29298843, 2018). "Immunohistochemical analysis of xenograft tumors revealed that IGF2BP2 knockdown promoted redifferentiation, as evidenced by a concomitant significant increase in the differentiation marker SLC5A5 (NIS) with a marked reduction in the cancer stem cell marker CD133, compared to shNC controls." (PMID 41522349, 2026). "Pan-cancer analysis of SLC5A5 across 34 cancer types revealed distinct expression patterns." (PMID 40321316, 2025). "Ion transporters, including SLC5A5, have been proposed as targets for cancer therapy." (PMID 40508009, 2025). "UROC1 (21%), HAO1 (15%), and SLC5A5 (14%) were the top three mutant genes in human cancers." (PMID 36313638, 2022). "In the Cancer Genome Atlas dataset, the expression level of FUT4 (CD15) mRNA was higher in the low/intermediate-risk group for recurrence than in the high-risk group and exhibited positive correlation with SLC5A5 (NIS) mRNA expression (p = 0.003)." (PMID 32486143, 2020). "SLC5A5 expression was significantly lower in carcinomas than that in normal adjacent counterparts." (PMID 29298843, 2018). "Functionally, IGF2BP2 promotes proliferation, suppresses thyroid differentiation genes (TSHR, SLC26A4, SLC5A5, TPO, PAX8, FOXE1, and NKX2.1), and enhances cancer stemness." (PMID 41522349, 2026). "In summary, the absence of BRAF and NRAS mutations in every carcinoma displaying NIS membrane staining at immunohistochemistry supports the assumption that the genetic background of tumors may be of major importance to SLC5A5 expression as well as to NIS targeting to the basolateral membrane." (PMID 29298843, 2018). "However, in poorly differentiated carcinomas and ATC, radioiodine refractoriness is frequent due to transcriptional silencing of thyroid differentiation genes (TDGs) and impaired SLC5A5/NIS trafficking to the plasma membrane, both hallmarks of thyroid dedifferentiation." (PMID 41147659, 2026).
adenocarcinoma (4 papers, 2007 to 2025). A common cancer characterized by the presence of malignant glandular cells. "We utilized immunohistochemistry to assess SLC5A5 expression in human SG tissues from Caucasian individuals with histologically healthy SG, chronic sialadenitis, pleomorphic adenoma, and adenocarcinoma." (PMID 40508009, 2025).
SLC5A5 also shares sentences with these, for which no sentence is quoted: anaplastic thyroid cancer (27 papers); multiple myeloma (26); ovarian carcinoma (22); prostate carcinoma (19); infection (18); glioma (14); breast tumors (13); hepatocellular carcinoma (11); acute myeloid leukemia (10); metastatic disease (10); pancreatic cancer (10); colon carcinoma (9); gastric cancer (8); goiter (7); hyperthyroidism (7); glioblastoma (6); Hashimoto thyroiditis (6); triple-negative breast carcinoma (6); autoimmune thyroid disease (5); medulloblastoma (5); melanoma (5); memory impairment (5); papillary carcinoma (5); brain tumor (4); colorectal cancer (4); leukemia (4); viral infection (4); adenoma (3); anaplastic carcinoma (3); Autoimmunity (3).
A further 84 diseases each share a sentence with SLC5A5 in 3 papers or fewer.